SOST (sclerostin)
Diseases named in the same sentence as SOST in open-access papers (continued):
Sharing a sentence is not in itself a finding about the gene and the disease.
sclerosteosis (continued). "Up to our knowledge, this is the first study of Egyptian patients with sclerosteosis describing the associated clinical traits and sclerosteosis causing mutations in SOST gene." (PMID 25984533, 2015). "We identified a novel mutation in SOST gene, in two affected Egyptian brothers with sclerosteosis, characterized by one nucleotide insertion resulting in a frameshift mutation." (PMID 25984533, 2015). "In 2014, i.e. 13 years after the identification of the first SOST mutations in individuals with sclerosteosis, the phase-II-clinical studies have been published." (PMID 26056589, 2014). "Loss-of-function mutations in sclerostin result in progressive bone overgrowth in diseases, such as sclerosteosis and van Buchem’s disease, which are also associated with hearing loss." (PMID 24788917, 2014). "Immediately thereafter, another study identified a 52 kb deletion downstream of the SOST gene causing reduced transcription in individuals with van Buchem disease, a skeletal dysplasia with similarities to sclerosteosis." (PMID 26056589, 2014). "Sclerosteosis is a rare high bone mass disease that is caused by inactivating mutations in the SOST gene." (PMID 23638027, 2013). "A naturally occurring Sclerostin variant, in which residue Cys142 - the sixth cysteine of the cystine-knot - is mutated to arginine, was found in a Turkish family suffering from Sclerosteosis." (PMID 24312339, 2013). "Based on a Sclerostin variant found in a Turkish family suffering from Sclerosteosis we generated a Sclerostin mutant with cysteines 84 and 142 exchanged thereby removing the third disulfide bond of the cystine-knot." (PMID 24312339, 2013). "Because of the high bone mass phenotype of individuals carrying SOST mutations, as in the case of sclerosteosis patients, or who lack SOST expression, in the case of Van Buchem's disease, it has been assumed that SCL is an inhibitor of bone formation." (PMID 21991382, 2011). "Interest in these highly specialized cells was elevated following the discovery that mutations in sclerostin (SOST), a protein expressed almost exclusively by mature osteocytes, cause the rare skeletal bone overgrowth conditions van Buchems disease and sclerosteosis." (PMID 37223031, 2023). "In fact, loss-of-function mutations in the sclerostin encoding gene, SOST, result in sclerosteosis and van Buchem disease (VBD), two autosomal recessive disorders that are characterized by hyperactive osteoblasts, high bone mass, and a thickening of the cortical bone." (PMID 37836411, 2023). "Loss-of-function mutations in this gene were found in patients with sclerosteosis and thus the physiological role of the SOST protein was hypothesized to be suppression of bone formation." (PMID 35563144, 2022). "Sclerosteosis has been linked to loss of function mutations in the SOST gene." (PMID 35208525, 2022). "Indeed, the first evidence of the role of SOST in bone was the identification of LoF mutations responsible for sclerosteosis, a very severe autosomal recessive disease, caused by a lack of functional sclerostin." (PMID 35052478, 2022). "Loss-of-function SOST mutations cause sclerosteosis, generally thought the more severe of the two disorders; in contrast, a 52-kb intronic deletion downstream of SOST, thought to disrupt post-transcriptional sclerostin processing, results in the milder phenotype of van Buchem’s disease." (PMID 33193107, 2020). "Since both sclerosteosis and van Buchem disease are genetic diseases caused by osteocytic sclerostin deficiency, the osteocyte could be the possible target cell to treat these diseases." (PMID 32733380, 2020). "Moreover, this is also reflected by pathological conditions caused by disrupting transcription of the SOST gene and subsequently Wnt signaling, such as sclerosteosis and the van Buchem syndrome (VBCH)." (PMID 33071985, 2020).
sclerosteosis (continued). "In sclerosteosis patients, extensive sequence analysis in this chromosomal region identified loss-of-function mutations in a previously unknown gene, now called the SOST gene." (PMID 32366042, 2020). "Overexpression of SOST gene in mice leads to low bone mass as a result of reduction in osteoblast activity; on the contrary, loss-of-function mutations of SOST gene lead to van Buchem disease and sclerosteosis, diseases distinguished by osteoblast hyperactivity and consequent increased bone density." (PMID 31703281, 2019). "Furthermore, sclerosteosis and Van Buchem disease, two rare bone disorders with mutations in or in close proximity of the SOST gene, leading to restricted expression of SOST, are characterized by progressive bone thickening due to enhanced bone formation." (PMID 31197079, 2019). "Sclerosteosis is a bone disease characterized by an overgrowth of bone and is caused by mutations in the gene and enhancer regions of the Wnt/β-catenin antagonist sclerostin (SOST)." (PMID 29868574, 2018). "Accordingly, loss of the bone-specific Wnt inhibitor sclerostin (SOST) due to inactivating SOST mutations or deletion of its regulatory region lead to sclerosteosis and Van Buchem disease, marked by high BMD with skeletal deformities such as jaw and cranial enlargement." (PMID 27533615, 2016). "Mutations in SOST gene coding for sclerostin are linked to sclerosteosis." (PMID 25984533, 2015). "SOST, positionally cloned as the gene causing Sclerosteosis is a regulator of bone density." (PMID 24789067, 2014). "Finally, sclerostin, the Wnt antagonist and the product of the sost gene that inhibits bone formation and plays a causal role in sclerosteosis, is transcriptionally activated by mef2c and is another osteocyte marker." (PMID 23533592, 2013). "BMP signaling is very important in bone development; it is not surprising that variations in BMP antagonists may affect skeletogenesis and BMD variations in humans (e.g., the sclerosteosis/van Buchem disease gene, which is caused by mutations in SOST)." (PMID 24138842, 2013). "Sclerosteosis is a rare high bone mass disorder that is caused by loss of Sclerostin expression." (PMID 23638027, 2013). "Van Buchem disease (sclerosteosis) is a hereditary sclerosing bone dysplasia, caused by loss-of-function mutations of the SOST gene, which codes the protein sclerostin." (PMID 40177730, 2025). "Sclerosteosis is caused by biallelic pathogenic variants in SOST, which result in the loss of a functional C-terminal domain necessary for the secretion of sclerostin protein from the endoplasmic reticulum." (PMID 40943101, 2025). "Sclerosteosis is caused by SOST mutations and loss of functional sclerostin, a protein that suppresses osteogenesis by antagonising Wnt/β-catenin signalling." (PMID 40189599, 2025). "Sclerostin exerts a direct anti-anabolic action on bone tissue by binding low-density lipoprotein-receptor-related protein (LRP4); in fact, some cases of sclerosteosis are caused by mutations in this protein." (PMID 38634076, 2024). "Sclerostin is also a key regulator of craniofacial bone morphology, and human mutations inactivating SOST cause sclerosteosis (van Buchem disease), with increased bone mass, mandibular enlargement, and reduced cranial foramen diameter." (PMID 38828726, 2024). "The sclerostin/SOST gene first appeared due to two rare bone overgrowth diseases, sclerosteosis and van Buchem disease, mapped to chromosome 17q12-q21." (PMID 37759285, 2023). "Conversely, low levels of sclerostin or SOST gene mutations can implicate several genetic skeletal disorders with high bone mineral density (BMD), such as sclerosteosis and van Buchem disease." (PMID 36835830, 2023). "Sclerostin loss‐of‐function is associated with sclerosteosis (OMIM# 269500) and dysregulation of sclerostin has been linked to Van Buchem Disease (OMIM# 239100), disorders of skeletal overgrowth." (PMID 35460154, 2022).
sclerosteosis (continued). "A sclerostin deficiency due to inactivating variants and a large deletion in the regulatory sequence of the SOST gene cause sclerosteosis 1 and van Buchem disease, respectively, which are characterized by osteosclerosis and a high bone mass." (PMID 36246908, 2022). "Instead, impaired binding between sclerostin and LRP4 has been verified in the mutations causing sclerosteosis, which would explain the severity of the effect." (PMID 35052478, 2022). "Sclerosteosis 2 has been mapped to the LRP4 gene where there is direct interaction between sclerostin and LRP4, and LRP4 facilitates sclerostin mediated WNT inhibition; which is implicated in LRP4 mutants." (PMID 35549993, 2022). "A recent study investigating the effectiveness of sclerostin replacement in a mouse model of sclerosteosis found that sclerostin replacement in mice partially corrected the high bone mass phenotype of affected mice." (PMID 35208525, 2022). "The SOST gene was initially identified in the late 1990s during the studies on sclerosteosis and Van Buchem disease, which are two rare hereditary diseases characterized by high bone mass." (PMID 35562828, 2022). "Though SOST dysregulation was identified as the gene responsible for sclerosteosis, its upregulation suppresses bone formation via canonical Wnt inhibition." (PMID 36497192, 2022). "The importance of SOST as a key regulator of bone remodeling is evident in sclerosteosis, a human genetic bone disorder characterized by high bone mass due to the lack of SOST." (PMID 35163708, 2022). "Sclerosteosis must be differentiated from VBCH, another craniotubular hyperostosis condition that is caused by the deletion of a SOST-specific regulatory element." (PMID 35208525, 2022). "Sclerostin, a product of the SOST gene, was initially discovered as the underlying mutation in the HBM disorder sclerosteosis and has since been targeted to treat postmenopausal osteoporosis in the form of romosozumab." (PMID 33538965, 2021). "In the current study, we performed a mutation analysis of the SOST and LRP4 genes in a sclerosteosis patient, identifying compound heterozygous variants in the first and third β-propeller domain of LRP4." (PMID 35052419, 2021). "The presence of congenital hand disorders in patients with sclerosteosis suggests that SOST is expressed in the developing embryo." (PMID 34830568, 2021). "Deletion of SOST using gene targeting resulted in a high bone mass phenotype similar to individuals with sclerosteosis and van Buchem’s disease." (PMID 33669283, 2021). "We identified only one sclerosteosis carrier, who manifested moderately high BMD due to a novel heterozygous nonsense SOST mutation predicted to either prematurely truncate sclerostin or cause nonsense-mediated decay." (PMID 33193107, 2020). "Studies on rare bone diseases, sclerosteosis, and van Buchem disease, have unraveled the role of sclerostin in bone homeostasis." (PMID 32733380, 2020). "First identified in patients suffering from sclerosteosis, SOST is a secreted glycoprotein that is predominantly expressed in osteocytes." (PMID 33097721, 2020). "Sclerostin, encoded by SOST, was initially identified from the study of patients with the heritable HBM disorder, sclerosteosis." (PMID 33658983, 2020). "SOST, the gene responsible for sclerosteosis and van Buchem disease, is localized on chromosome 17q12-q21, and encodes sclerostin protein." (PMID 32733380, 2020). "SOST and its gene product, Sclerostin, were identified by examining genes involved in sclerosteosis." (PMID 32708317, 2020). "Furthermore, the patients suffering from sclerosteosis and van Buchem disease (also known as hyperostosis corticalis generalisata), characterized by high bone mass, present a loss of the SOST gene function and SOST deletion on chromosome 17q (17q12–21 deletion), respectively." (PMID 33066607, 2020).
sclerosteosis (continued). "Understanding the molecular biology of sclerosteosis and van Buchem’s disease has led to the development of monoclonal antibodies against sclerostin, which act to suppress the inhibitory action of sclerostin on Wnt signaling, allowing gains in bone formation." (PMID 33193107, 2020). "SOST KO mice (SOST-KO) exhibited an increased bone mass phenotype due to enhanced osteogenesis, similar to the human sclerosteosis phenotype." (PMID 31698687, 2019). "Van Buchem disease / sclerosteosis and the discovery of the SOST gene are a great example of novel gene identification leading to novel targets for common conditions." (PMID 31888683, 2019). "The human genetic bone disorder, sclerosteosis, provides an insight into the role of SOST in bone regulatory processes." (PMID 29844945, 2018). "Osteocytes express a protein called sclerostin, whose name derives from the disease sclerosteosis, a rare severe and progressive craniotubular hyperostosis with an autosomal recessive inheritance." (PMID 27558933, 2016). "Sclerostin was initially discovered from diseases with a bone-overgrowth phenotype, sclerosteosis and the van Buchem disease." (PMID 27558933, 2016). "In this study, we sequenced the coding and exon-intron boundaries sequence of the entire SOST gene in two Egyptian brothers, offspring of consanguineous parents, with sclerosteosis." (PMID 25984533, 2015). "The first report identified two inactivating mutations causing an autosomal recessive sclerosing bone dysplasia (sclerosteosis), and the thereby identified gene was termed SOST (Sclerostin)." (PMID 26056589, 2014). "Sclerostin was discovered from genetic screenings of patients showing increased bone densities, revealing that patients suffering from van Buchem disease or Sclerosteosis lack or have decreased levels of Sclerostin." (PMID 24312339, 2013). "Loss of function mutations in either the sclerostin-encoding gene, SOST, or in its regulatory sequence cause the human syndromes known as sclerosteosis and van Buchem disease, both of which are characterized by high bone mass." (PMID 23308287, 2013). "There aregood examples of SOST inhibition in diseases suchas Van Buchem and Sclerosteosis, where both diseases, despite an increase of Wnt signaling activity, increase bone mass with no other problems ortumor." (PMID 24027669, 2013). "SOST mutations lead to severe HBM disorders, sclerosteosis and van Buchem disease, while DKK1 is shown to associate with bone lesions in multiple myeloma." (PMID 22487062, 2012). "Diseases of high bone mass are rare and include sclerosteosis due to deletion of SOST and autosomal dominant high bone mass due to gain-of-function mutations in LRP5." (PMID 22876197, 2012). "Sclerostin (SCL) is the product of the SOST gene, mutations in which cause the high bone mass disease in humans, sclerosteosis." (PMID 21991382, 2011). "We carried out real-time quantitative reverse-transcriptase PCR (Q-RT-PCR) validation for two genes, SOST (sclerosteosis) and RUNX3 (runt-related transcription factor 3) which each were significantly altered according to the microarray data." (PMID 17634102, 2007). "Furthermore, loss-of-function or loss-of-expression mutations of SOST (sclerostin), a secreted antagonist that prevents WNTs from binding to LRP5, cause high bone mass in sclerosteosis or Van Buchem disease, respectively." (PMID 39434845, 2024). "Chromosomal region 17q12-q21 is responsible for two similar hyperostosis conditions, sclerosteosis and van Buchem disease (VBCH); however, they involve different loss of function mutations in the SOST gene (coding region in sclerosteosis and regulatory element in VBCH)." (PMID 35208525, 2022). "SOST expression has also been found in the developing embryo, where it plays a role in limb patterning, which explains the cases of syndactyly among patients with sclerosteosis." (PMID 35052478, 2022).
sclerosteosis (continued). "Ten years after the identification of SOST as the disease-causing gene, pathogenic variants in LRP4, which encodes the low-density lipoprotein receptor-related protein 4 (LRP4), were identified in SOST-negative sclerosteosis patients." (PMID 35052419, 2021). "However, a greater risk of vascular calcification has not been reported in sclerostin KO mice or in patients suffering from sclerosteosis or Van Buchem disease, related to a decrease in sclerostin expression." (PMID 33114755, 2020). "Sclerostin (SOST) was discovered during the study of sclerosteosis and Van Buchem disease." (PMID 33409280, 2020). "Sclerosteosis and van Buchem disease are two rare, autosomal recessive, sclerosing bone disorders characterized by high bone mass and increased bone strength caused by defects of the SOST gene in chromosome 17q12-21 that encodes sclerostin." (PMID 27016922, 2016). "Sclerosteosis patients lack sclerostin due to homozygous mutations in the sclerostin-encoding gene SOST, but heterozygous carriers have an increased bone mineral density suggesting a gene dosage effect for sclerostin." (PMID 27558933, 2016). "The role of sclerostin in the modulation of the Wnt/β-catenin dependent pathway came to light specifically through the study of sclerosteosis and van Buchem disease, two rare genetic disorders associated with high levels of BMD and an associated low risk of fracture." (PMID 27313945, 2016). "These experiments, however, show that the mutant protein is only poorly secreted, possibly indicating that the Sclerosteosis in the patients might be due to a Sclerostin dosage effect." (PMID 24312339, 2013). "Sclerostin, originally identified in genetic screens of two diseases characterized by strong increased bone mass, Sclerosteosis and van Buchem syndrome, could provide such a target." (PMID 24312339, 2013). "The sclerosing bone dysplasias sclerosteosis and van Buchem disease are caused by decreased or absent Sclerostin expression, and thereby implicate Sclerostin as a very potent inhibitor of bone formation." (PMID 21436889, 2011). "Sclerosteosis, an autosomal recessive disorder characterized by increased bone mass, mainly in the skull and in long bones, results from a mutation in the SOST gene, which codes for sclerostin." (PMID 21209785, 2010). "In this issue, J. J. Mason and B. O. Williams describe a rare genetic disorder, sclerosteosis, resulting from a mutation of the SOST gene that encodes for sclerostin, and van Buchem disease, a related disorder caused by a mutation closely linked to SOST on chromosome 17q11.2." (PMID 21234374, 2010). "Regarding the effects, of sclerostin it is known that sclerostin deletion in mice induces an increase in bone mineral density, whereas its overexpression decreases bone mass, and genetic mutations affecting the gene SOST (gene encoding sclerostin) induce sclerosteosis and van Buchem disease." (PMID 36829932, 2023). "Sclerostin has been recognized as a negative regulator of bone formation through inhibition of canonical Wnt signaling pathway in osteoblast lineage cells, and its role was first recognized in the study of two rare high bone mass disorders, namely sclerosteosis and van Buchem’s disease." (PMID 34830568, 2021). "The marked prognathism displayed by our patient 2 resembles that observed in sclerosteosis (OMIM 269500), van Buchem disease (OMIM 239100), or craniodiaphyseal dysplasia (OMIM 122860), the most severe and lethal form of craniotubular dysplasia, which are all caused by SOST deficiency." (PMID 29341480, 2018). "To test irrespectively of the cause of Sclerosteosis in these patients whether the cystine-knot is functionally important for Sclerostin activity and LRP6 binding, we first prepared a Sclerostin variant with Cys142 mutated to alanine employing our bacterial expression system." (PMID 24312339, 2013).